IL6 (interleukin 6)
Diseases named in the same sentence as IL6 in open-access papers (continued):
Sharing a sentence is not in itself a finding about the gene and the disease.
keratoconus (continued). "In the present work, our purpose was to analyze the effects of riboflavin UV-A illumination on mRNA and protein expression of healthy (HCFs) and keratoconus human corneal fibroblasts (KC-HCFs), concerning the inflammatory markers NF-κB, iNOS, IL-6, and collagen 1 and 5 (Col 1/Col 5)." (PMID 33443628, 2021). "Moreover, IL-6 levels were increased in the tear fluid of keratoconus patients as indicated in this study and reported earlier." (PMID 21298010, 2011). "Also, TNF-alpha and IL-6 can also be found in atopic and vernal keratoconjunctivitis, suggesting that keratoconus could be related to allergies and to increased level of serum IgE." (PMID 27563164, 2016). "In the current study, we have determined the associations between nine mediators (IL-6, IL-10, CXCL8/IL-8, CCL5/RANTES, MMP-9, MMP-13, TIMP-1, t-PA, and PAI-1) in the tear fluid of keratoconic patients covering the whole spectrum of the disease (from subclinical to manifest keratoconus)." (PMID 26881061, 2016). "For example, concentrations of IL-6, IL-8, IL-1β, and TNF-α are markedly elevated in keratoconus patients relative to healthy controls." (PMID 40547926, 2025). "Increased levels of inflammatory mediators, such as immunoglobulin E (IgE), cytokines (IL-1, IL-6 and TNF-alpha) and proteolytic enzymes (MMP-9), have been found in the tears of keratoconus patients." (PMID 36138270, 2023). "Increased levels of inflammatory mediators such as IgE, cytokines (IL-1, IL-6 and TNF-alpha) and proteolytic enzymes (MMP-9) have been found in the tears of keratoconus patients." (PMID 36138270, 2023). "To address this controversial issue at the single-cell level, we first surveyed the predominant source of several reported cytokines increased in keratoconus samples, including IL1, IL6, IL10, TNF-α and TGF-β37,75,76." (PMID 35821117, 2022). "The means of IFN gamma, IL-10, IL-1 beta, IL-4, IL-6, and TNF alpha had a significant difference between the keratoconus patients and the normal subjects." (PMID 30245588, 2018). "On the contrary, multiple recent studies published evidence that highlight a possible inflammatory etiology marked through the presence of proinflammatory cytokines such as IL-6, IL-1 beta, IFN gamma, and TNF alpha in the tear film of keratoconus patients." (PMID 30245588, 2018). "Our aim was to determine the concentration of IL-4, IL-6, IL-10, RANTES, IFN gamma, and TNF alpha in the tear film of patients with keratoconus and their first degree family members." (PMID 30245588, 2018). "Levels of IL-6 and IL-17 were increased, while IL-12, CCL5, and IL-13 were decreased in keratoconus tear fluids compared with control." (PMID 27403376, 2016). "A presumed progression risk factor of keratoconus is the contact lens wear, especially rigid gas permeable contact lenses that induce the upregulation of IL-6, TNF-alpha, ICAM-1, and VCAM-1 in the tears of subjects with keratoconus." (PMID 27563164, 2016). "Partly in line with these results, increased tear levels of MMP-1, MMP-3, MMP-7, MMP-9, and MMP-13; IL-4, IL-5, IL-6, and IL-8, and TNF-α, -β were found in keratoconus." (PMID 26881061, 2016). "The study showed increased levels of gelatinases and collagenases (1.9 times higher), as well as elevated MMPs, cytokines (MMP-1, MMP-3, MMP-7, MMP-13, and IL-6), and TNF-alpha and TNF-beta in the keratoconus group compared with the normal group." (PMID 27563164, 2016). "Recent studies have suggested pro-inflammatory factors as key to keratoconus pathogenesis based on their findings of elevated interleukin (IL)-6, tumor necrosis factor (TNF)-α and matrix metalloproteinase (MMP)-9 in the tear fluid of keratoconus patients." (PMID 21298010, 2011). "Our findings confirm increased IL-6, but dispute earlier reports of increased TNF-α, and suggest a cytokine imbalance in keratoconus disrupting corneal homeostasis." (PMID 21298010, 2011).
keratoconus (continued). "Others have examined isolated cytokines by conventional sandwich ELISA and reported concentrations of IL-6, TNF-α and IL-10 in control and keratoconus subjects." (PMID 21298010, 2011). "Perhaps labelling keratoconus as a non-inflammatory disease is inappropriate, considering the statistically significant reduction in IL-6 concentration in each of our studied time periods: after seven days, after a month, and after 3, 6, 9 and 12 months." (PMID 38256126, 2024). "Besides the intraocular IL-6 level, tear IL-6 level is higher in surface ocular diseases, such as DED, keratitis, and keratoconus." (PMID 37092464, 2023). "Moreover, overexpression of IL-6 and TNF-α in tears of subclinical keratoconus indicate that chronic inflammatory events are involved in the pathogenesis of keratoconus." (PMID 36904299, 2023). "In addition to the intraocular IL-6 levels, it was also confirmed that tear levels of IL-6 was higher among surface ocular diseases, including conjunctivitis, dry eye disease (DED), keratoconus (KC) and keratitis." (PMID 33060644, 2020). "In the keratoconus group, using the CORR procedure, we found statistically strong correlations of IL-6 lacrimal concentrations with the disease stage (r = 0.56, p < 0.01), keratometry (r = 0.55, p < 0.02), pachymetry (r = −0.64, p < 0.048), and corneal hysteresis (r = −0.53, p < 0.02)." (PMID 30245588, 2018). "Therefore, accumulated information about these markers should be considered for application in diagnosis e.g., elevated MMP9 and IL6 along with a reduction in markers such as LOX, SFRP1 in tears can give a specific diagnosis of keratoconus." (PMID 27493978, 2016). "The study revealed also a negative association between IL-6 and Th1, respectively, between MMP-13 and keratoconus index (KI)." (PMID 27563164, 2016). "Interleukin (IL)-1β, IL-4, IL-6, IL-10, IL-12, IL-13, IL-17, interferon (IFN)-γ, chemokine C-C motif ligand 5 (CCL5) and tumor necrosis factor (TNF)-α were tested in tear samples and sera of keratoconus and control individuals by multiplex immuno-bead assays." (PMID 21298010, 2011). "These factors may contribute to the pathogenesis of keratoconus; furthermore, studies have shown that post-rubbing tear samples from normal eyes exhibit high concentrations of IL-8, MMP-13, IL-6, TNF-α, and epithelial growth factor compared to contralateral control eyes." (PMID 40343259, 2025). "Elevated levels of interleukin- (IL-) 1b, IL-4, IL-5, IL-6, IL-8, and IL-17; tumor necrosis factor (TNF)-α, -β; interferon- (IFN-) γ; matrix metalloproteinase- (MMP-) 1, MMP-3, MMP-7, MMP-9, and MMP-13; Cathepsin B; and Lipocalin-1 have been found in the tears of patients with keratoconus." (PMID 26881061, 2016). "Indeed, whether relative TGF-β and IL-6 levels are altered sufficiently in keratoconus ocular tissues are not known at this time." (PMID 21298010, 2011).
Miscarriage (34 papers, 2014 to 2026). A pregnancy that ends at a stage in which the fetus is incapable of surviving on its own, defined as the spontaneous loss of a fetus before the 22th week of pregnancy. "Elevated levels of IL-6 are associated with increased miscarriage and preterm birth, likely playing a modulating role during embryo implantation and placental development." (PMID 41440029, 2025). "In our study, age and interleukin-6 demonstrated significant associations with pregnancy outcomes in women afflicted with TAI-positive recurrent spontaneous abortion (RSA)." (PMID 38298186, 2023). "Mutant SNPs in TLR9, IL-10, TLR2, IL-6, and IL-8 genes were found to have statistically significant effect on the risk of miscarriage with help of multiple logistic regression." (PMID 30116270, 2018). "Previous studies have shown association between increased production of Th1 cytokines (including IL-6 and IL-8) and risk of miscarriage." (PMID 30116270, 2018). "Measuring immunomodulatory factors such as HLA‐G, TGF‐β and IL‐6 may help identify male partners whose seminal immune environment is associated with suboptimal implantation or higher miscarriage risk." (PMID 41395839, 2025). "However, abnormally high expression of IL-6 is often associated with recurrent spontaneous abortion (RSA) and RIF." (PMID 35898466, 2022). "Complement c4 was identified as a risk factor for miscarriage in TAI-negative RSA women, whereas IL-6 was a protective factor for the same in RSA women with TAI." (PMID 38298186, 2023). "In line with this, in a culture of PBMCs from women with chronic inflammatory disease, such as unexplained recurrent spontaneous miscarriage (uRSM), dydrogesterone and progesterone up-regulated IL-6 but down-regulated IL-17A and IL-23." (PMID 37298830, 2023). "Of the 83 patients included in the study, 11 had a miscarriage in early pregnancy and their IL-6 concentration in the follicular fluid exceeded 10 ng/mL." (PMID 35866786, 2022). "In a previous study, the levels of IL-6 in the blood serum of patients with miscarriage were significantly higher than those in normal pregnancy (Drozdzik, Szlarb & Kurzawski, 2013)." (PMID 35186454, 2022). "In our study, the highest concentration of IL-6 in the follicular fluid was 44 ng/ml, and the outcome of this process was a miscarriage." (PMID 35866786, 2022). "Whitcomb tested the serum of women 10 days before miscarriage, and found low levels of several pro-inflammatory cytokines, IL-1β, IL-4, IL-6, IFN-γ and TNF- α, which confirms our findings." (PMID 34300281, 2021). "First‐trimester miscarriage is associated with reduced IL‐6 and CXCL8 production, and lower IL‐6 transcription is evident in the uterine endometrium of women with recurrent miscarriages, compared with fertile women." (PMID 34408876, 2021). "The multiple logistic regression analysis has also shown that the following double interactions showed statistically significant association with the risk of miscarriage: TLR9 and IL-10; TLR9 and IL-8; TLR9 and IL-6; and IL-10 and TLR4." (PMID 30116270, 2018). "The following double genetic interactions showed statistically significant association with the risk of miscarriage: TLR9 and IL-6; TLR9 and IL-8; TLR9 and IL-10; and IL-10 and TLR4." (PMID 30116270, 2018). "Levels of IL-6 in the mid-secretory-phase endometrium are lower in women with previous recurrent miscarriage." (PMID 30322386, 2018). "TLR2, TLR4, IL-6, IL-8, and PGR SNPs can also affect the risk of miscarriage, but in less extent than TLR9 and IL-10." (PMID 30116270, 2018). "TLR2, TLR4, IL-6, IL-8, and PGR SNPs were identified as secondary factors that can also affect the risk of miscarriage." (PMID 30116270, 2018). "TNF -238G > A, TNF -308G > A, IL1B -511 T > C, IL1B 3954C > T, IL6 -174G > C, IL6 -634C > G, IL10 -1082A > G and IFNG 874A > T polymorphisms were genotyped on 775 women with idiopathic recurrent miscarriage and 805 healthy parous control women." (PMID 29017513, 2017).
Miscarriage (continued). "Additionally, a study found that women with a history of miscarriage exhibited elevated levels of IL-6, IL-17, and TGF-β compared to the control group." (PMID 39596022, 2024). "As shown in our study, in the PBMCs of menopausal women, IL-6 was stimulated by synthetic progestins but not by P4, which is partially consistent with the previously obtained data of IL-6 increasing in PBMCs under the influence of P4 and dydrogesterone in women with recurrent miscarriages." (PMID 37298830, 2023). "It is believed that IL-6 is one of the factors involved in the pathology of miscarriage." (PMID 35186454, 2022). "In our work, it was true that no statistical differences in serum Il-6 concentration were found in the study and control group, but in correlation with Il-10 it was found that in missed miscarriage, the increase in Il-10 concentration was followed by a significant increase in Il-6 concentration." (PMID 34444287, 2021). "Moreover, a higher IL-12/IL-6 ratio (Th1-biased state) was found in HEV-infected mice with miscarriages than in uninfected MOCK or HEV-infected mice with normal deliveries." (PMID 31108901, 2019). "In addition IL1 β, IL-6, IL-10 and CXCL8 (IL-8) have previously been examined in maternal circulation in association with miscarriage." (PMID 24699265, 2014). "Th1 cytokine levels in women with miscarriage compared to the control group reached slightly higher values for INF-γ, Il-1β and slightly lower for Il-6 and TNF-α." (PMID 34444287, 2021). "Studies done with lymphocytes isolated from women with recurrent miscarriage indicate that dydrogesterone inhibits the production of INF-γ, TNFα, IL-4, and IL-6 modifying the Th1/Th2 ratio." (PMID 26446923, 2015). "In conclusion, we have found plasma concentrations of the cytokines IL-1β, IL-6 and IL-10, and the chemokines, CXCL8, CCL2, CCL5, CCL7, CX3CL1 cannot predict subsequent miscarriage." (PMID 24699265, 2014). "Other reports have noted low and non-detectable circulating levels of several cytokines including IL-1β, IL-6, IFN-γ and TNF-α and lack of consistent associations with miscarriage risk." (PMID 24699265, 2014). "TLR 9 GG and IL-6 GG interaction (z = −3.078, p=0.002) and TLR 9 GG and IL-6 GC interaction (z = −2.8, p=0.005) had a statistically significant negative effect on the risk of miscarriage." (PMID 30116270, 2018). "In the miscarriage model, ML345 not only decreased IL-1β levels but also reduced IL-6 and TNF, which are independent of NLRP3." (PMID 41231359, 2025). "MDC1 from miscarriage patients had a significant reduced capacity to secrete IL-1β, IL-6, IL-10, and TNF, while MDC2 from miscarriage patients did not behave differentially from MDC2 of normal pregnant women." (PMID 31681319, 2019).
obstructive sleep apnea (34 papers, 2009 to 2025). "At a physiological level, OSA and OSAS (Obstructive Sleep Apnea Syndrome) are associated with intermittent hypoxemia, higher serum and plasma interleukin-6 levels, and higher serum and plasma TNF-alpha levels, always compared to healthy controls." (PMID 33919250, 2021). "Increased pain sensation related to sleep deprivation is reported to be associated with an increase in IL-6; an inflammatory marker can be elevated in patients with obstructive sleep apnea (OSA) and low 25(OH)D." (PMID 30275418, 2018). "The cardiovascular complications that frequently accompany obstructive sleep apnea syndrome (OSAS) are thought to develop as a result of inflammatory stress associated with cytokines such as IL-6 and TNF-α." (PMID 24895539, 2014). "By lowering inflammatory cytokines such as CRP and IL-6, probiotics may help attenuate airway inflammation and collapsibility associated with obstructive sleep apnea." (PMID 40863567, 2025). "It is shown that certain inflammatory parameters including CRP, fibrinogen, IL-6, and Tumor Necrosis Factor-α (TNF-α) are linked with higher cardiovascular risk in patients with obstructive sleep apnea." (PMID 35694268, 2022). "In another study, lower adropin plasma levels and increased inflammation markers such as TNFα and interleukin-6 (IL-6) were reported in male patients with moderate and severe obstructive sleep apnea, compared to healthy individuals." (PMID 35955453, 2022). "It is the same as a previous meta-analysis that either children or adults with obstructive sleep apnea syndrome had higher serum/plasma IL-6 levels compared to healthy controls." (PMID 34880901, 2021). "A negative correlation between circulating adropin and proinflammatory signals, such as TNFα or IL-6, was reported in patients with obstructive sleep apnea." (PMID 34199277, 2021). "In one study that evaluated the association between polymorphisms in interleukin-6 (IL6) and obstructive sleep apnea, IL6 (rs2069849) was associated with a decreased risk for obstructive sleep apnea, after adjusting for body mass index assuming an additive model." (PMID 22844404, 2012). "One of the proposed mechanisms was an inflammatory response to obstructive sleep apnea (OSA), i.e., mediating by cytokines, such as tumor necrosis factor (TNF-α) and interleukin 6 (IL-6)." (PMID 36061896, 2022). "After the analysis of the levels of pro and anti-inflammatory markers (IL-1β, IL-4, IL-6, IL-8, IL-10, Il-15, TNF-α, CRP, α1-GP) in the tonsils, we observed higher levels of markers IL-8 and IL-10 in pediatric patients with obstructive sleep apnea syndrome." (PMID 30213594, 2020). "Resistin is significantly correlated with IL-6 and ICAM-1 in patients with obstructive sleep apnea syndrome." (PMID 27549428, 2016). "It is noteworthy that two of these cytokines, IL-6 and TNF-alpha, are also elevated in the serum of individuals with obstructive sleep apnea and sleep deprivation and correlate with fatigue and sleepiness in general population studies." (PMID 23316361, 2012). "Patients with obstructive sleep apnea show significant increases in serum levels of TNF-α, IL-1β, and IL-6." (PMID 22578011, 2012). "Other studies on obstructive sleep apnea syndrome suggested that patients with obstructive sleep apnea syndrome showed high serum levels of tumor necrosis factor-α (TNF-α), IL-6, CRP, and spontaneous production of IL-6 by monocytes compared with obese control subjects." (PMID 34589489, 2021). "The objective of this study was to determine the independent and incremental values of advanced oxidative protein product (AOPP), interleukin 6 (IL-6), and growth differentiation factor 15 (GDF15) in identifying arteriosclerosis in patients with obstructive sleep apnea (OSA)." (PMID 38378599, 2024). "Verify the levels of the inflammatory markers, IL-1β, IL-4, IL-6, IL-8, IL-10, IL-15, TNF-α, CRP and α1-GP, in the tonsils of children with and without obstructive sleep apnea syndrome." (PMID 30213594, 2020).